HNF1A (HNF1 homeobox A)
Diseases named in the same sentence as HNF1A in open-access papers (continued):
Sharing a sentence is not in itself a finding about the gene and the disease.
diabetes (continued). "More than 20 causal genes have been linked to monogenic diabetes so far, the strongest evidence and highest prevalence having the transcription factors HNF1A, HNF4A, HNF1B and the GCK gene encoding the glucokinase enzyme." (PMID 34440499, 2021). "The other heterozygous c.8C > A variant in HNF1A was identified in a 26-year-old Kuwaiti woman diagnosed with T2D who had a strong family history of diabetes." (PMID 34373539, 2021). "The Ser6Arg mutation of the HNF1A gene was found here in a family with diabetes mellitus in five generations in proband P19 (family J)." (PMID 33477506, 2021). "Genome-wide association studies have also shown a possible link between developing diabetes mellitus and pancreatic cancer through gene mutations in the hepatocyte nuclear factor 1 alpha (HNF1A) gene." (PMID 33440856, 2021). "In pancreas ß-islet cells, HNF1A contributes to insulin secretion in response to glucose and is associated with maturity-onset diabetes of the young-like diabetes." (PMID 34493690, 2021). "Here, we developed a novel LC-based workflow to analyze blood plasma N-glycan fucosylation in 320 diabetes cases with clinical features matching those at risk of HNF1A-MODY." (PMID 33765222, 2021). "Heterozygous mutations in the genes encoding the transcription factors hepatic nuclear factor-4α and -1α (HNF4A and HNF1A, respectively) result in reduced insulin secretion and mutation carriers develop diabetes in childhood or early adulthood." (PMID 33569631, 2021). "Even though about 375 mutations in the HNF1A gene have been reported to date, 198 of these are associated with HNF1A-MODY or diabetes in general (based on ClinVar data)." (PMID 34299172, 2021). "Mutations in HNF1A lead to decreased insulin secretion, and progressive damage of beta cells and thus cause the onset of diabetes." (PMID 31754975, 2020). "A correct diabetes diagnosis is important because a mutation in HNF1A leads to clinical actions involving diagnosis, treatment, and genetic counselling." (PMID 32910913, 2020). "Diabetes caused by mutations in the HNF4A gene is considerably less common than HNF1A (5% to 10% of the cases), but should be considered whenever clinical characteristics of HNF1A are present and genetic analysis does not detect a mutation in this gene." (PMID 32528556, 2020). "Patients with HNF1A-MODY are usually at risk of developing diabetes-related complications because glycemic control worsens over time." (PMID 33292863, 2020). "Previously we have demonstrated significant increases in extracellular novel diabetes-linked miRNAs miR-224 and miR-103-3p in biofluids of patients with HNF1A-MODY primary beta-cell dysfunction, capable of differentiating these patients from T2DM23,24." (PMID 31969632, 2020). "Our proof-of-principle analyses facilitated informative stratification of HNF1A variants along the continuum, allowing improved evaluation of clinical significance, management, and precision medicine in diabetes clinics." (PMID 32910913, 2020). "This study aimed to investigate the cosegregation of HNF1A mutations with diabetes and HCA in two families." (PMID 31754975, 2020). "Human heterozygous HNF1A loss‐of‐function mutations cause diabetes, in part because HNF1A promotes pancreatic β‐cell proliferation, and mouse Hnf1a mutations prevent the formation of large T antigen‐driven β‐cell tumors." (PMID 32154941, 2020). "Two patients suffering from HCA and diabetes were screened for HNF1A germline and somatic mutations using direct sequence analysis and methylation-specific multiplex-ligation-dependent probe amplification (MS-MLPA) assay." (PMID 31754975, 2020). "HNF1A‐MODY is associated with diabetes onset before the age of 25 years and gestational diabetes, and is treated best with sulfonylurea derivatives." (PMID 31483937, 2019). "HNF1A gene SNPs (p.I27L, p.A98V and p.S487 N) were inconsistently associated with impaired glucose tolerance and having diabetes." (PMID 31109344, 2019).
diabetes (continued). "Hyperinsulinaemic hypoglycaemia in infancy and diabetes in later life have been reported in patients with HNF1A, HNF4A and ABCC8 mutations." (PMID 29739729, 2019). "HNF1A gene single nucleotide polymorphisms (SNPs) were modestly associated with Type 2 diabetes mellitus (T2DM) and glycemic features in different populations." (PMID 31109344, 2019). "A German-Austrian study reported that age at onset of diabetes (10.9 years) was found to be younger in p.I27L + p.S487 N ± p.A98V carriers, as compared with HNF1A mutation (14 years)." (PMID 31109344, 2019). "Although the exact mechanism linking HNF-1α mutations with the development of diabetes is partially known, there are a number of studies that suspect structural mutations as a plausible explanation." (PMID 31685031, 2019). "Rare mutations of the HNF1A gene cause a monogenic form of diabetes as Type 3 maturity-onset-diabetes of the young (MODY3)." (PMID 31109344, 2019). "The discussion in this section implicates HNF-1α mutations in accumulating lipids in the liver, promoting diabetes, and raising glucose uptake that can better help survive cancerous cells." (PMID 31685031, 2019). "Mutations in HNF-1α are well-acknowledged in diabetes and are frequently mentioned in liver malignancies." (PMID 31685031, 2019). "HNF1A is identified as a regulator of the PD pathways for cancer, high cholesterol, and diabetes, while mutations of HNF1A are known to cause hereditary cancers and diabetes, and variants of HNF1A are strongly associated with cholesterol level in GWAS." (PMID 29325558, 2018). "We also had difficulty in recruiting family members of the probands to establish co-segregation of the variant with diabetes for all the HNF1A variants found." (PMID 29666556, 2018). "Compared to type 2 diabetes, diabetes caused by HNF1A variants is considerably more responsive to sulphonylurea drugs." (PMID 30487145, 2018). "Disease-causing variant alleles in HNF1A demonstrate a high penetrance, so 63% of variant carriers develop diabetes before 25 years of age, and 96% before the age of 55 years." (PMID 29666556, 2018). "Rare variants in the HNF1A gene can cause monogenic diabetes, while common variants confer type 2 diabetes risk." (PMID 30143652, 2018). "In this study we aimed to describe the characteristics of young adults diagnosed with diabetes before the age of 45 years, who have rare HNF1A allele variants, and estimate the prevalence of HNF1A-MODY in Croatia." (PMID 29666556, 2018). "Maturity onset diabetes of the young due to HNF1A mutations (HNF1A-MODY) is the most frequent form of monogenic diabetes in adults." (PMID 29666556, 2018). "Loss of function mutations in HNF1A cause the most common form of monogenic diabetes (HNF-1A-MODY;MODY3), a disorder characterized by reduced glucose-stimulated insulin secretion." (PMID 30143652, 2018). "Among subjects with an HNF1A variant, 12 had at least a two-generational family history of diabetes, whilst detailed family histories were unavailable for one proband due to loss of contact with relatives." (PMID 29666556, 2018). "Earlier, it was demonstrated that patients with HNF1α mutations develop diabetes after the first decade, preceded by abnormal glucose-induced insulin secretion." (PMID 29867778, 2018). "A 46-yr-old female with elevated glucose and a significant family history of diabetes was found to be heterozygous for a pathogenic HNF1A (MIM: 142410) variant." (PMID 30487145, 2018). "It has been previously reported that patients with diabetes caused by HNF1A variants are fivefold more sensitive to sulphonylureas and typically need a much lower dose of the drug to prevent hypoglycemia." (PMID 30487145, 2018). "This new knowledge is highly relevant for precision medicine in diabetes as a novel mechanism for HNF-1A regulation and altered function by PIASγ, which reveal potential new targets for drug development in HNF-1A associated diabetes." (PMID 30143652, 2018).
diabetes (continued). "Fajans revealed the association of HNF1α gene mutation with MODY 3 diabetes by conducting linkage analysis of R-W pedigree." (PMID 29867778, 2018). "RFX6 heterozygotes have reduced penetrance of diabetes compared to common HNF1A and HNF4A-MODY mutations (27, 70 and 55% at 25 years of age, respectively)." (PMID 29026101, 2017). "Common variants in the monogenic diabetes genes HNF4A and WFS1, and a low-frequency variant in the HNF1A gene have also been associated with risk for T2D, highlighting the genetic overlap between monogenic diabetes and T2D." (PMID 29207974, 2017). "Three HNF1A isoforms were affected when the mutations were located in exon 1–6, and the diagnosis age of diabetes were younger than those with missense mutations involving one or two isoforms." (PMID 28105082, 2017). "Shepherd indicates that HNF-1α mutations are highly penetrant, with 63 % of mutation carriers having diabetes by the age of 25 years, 78.6 % by 35 years, and 95.5 % by 55 years." (PMID 27148439, 2016). "HNF1A is known to regulate numerous hepatic genes and heterozygous HNF1A mutations cause pancreatic-islet beta-cell dysfunction and monogenic diabetes." (PMID 26872257, 2016). "To reduce confounding biases, we adjusted both non-modifiable risk factors (age and sex) and conventional risk factors (hypertension, diabetes, and etc.)during association analysis between HNF1A and ischemic stroke." (PMID 27460564, 2016). "Most importantly, our results show that a single genetic locus can completely suppress diabetes in Hnf1a-deficiency." (PMID 27667715, 2016). "Positive C‐peptide is used to assess ongoing endogenous insulin secretion, and is likely to be present in patients with diabetes caused by HNF1A and HNF4A mutations." (PMID 27330718, 2016). "Mutation p.T130I was associated with both early-onset and late-onset diabetes and caused downregulated HNF4A expression, whereas HNF1A polymorphisms p.I27L and p.S487N were associated with the age of diagnosis of diabetes." (PMID 26981542, 2016). "Since this deletion is relatively large (1.3% of exon 7) and is located in the carboxyl-terminal transactivation domain, which is crucial for HNF1A function, it is highly probably that this is a causative variant of diabetes in this subject." (PMID 26942212, 2016). "In particular, we identified and characterized a major locus that is able to suppress the diabetes linked to Hnf1a-deficiency." (PMID 27667715, 2016). "Maturity Onset Diabetes of the Young type 3 (MODY3), linked to mutations in the transcription factor HNF1A, is the most prevalent form of monogenic diabetes mellitus." (PMID 27667715, 2016). "Our results showed that resistant mutant mice suppressed diabetes in spite of the overexpression of Ghrl, a hormone whose antagonist had been shown to be able to normalize insulin secretion and hyperglycemia in Hnf1a deficiency." (PMID 27667715, 2016). "Progressive beta-cell dysfunction and cell death, with impaired glucose-stimulated insulin secretion response and resulting hyperglycemia, is the hallmark and primary cause of diabetes and chronic related complications observed in HNF1α-MODY patients." (PMID 27551471, 2015). "The HNF1A gene is an important hepatic nuclear transcription factor that has been associated in GWAS with lipids and diabetes." (PMID 25768928, 2015). "Using an unbiased array approach, we previously identified elevated levels of miR-224 and miR-103 to be associated with a monogenic form of diabetes; HNF1A-MODY." (PMID 26110317, 2015). "HNF1A-maturity-onset diabetes of the young (HNF1A-MODY) is the most common monogenic form of diabetes resulting from mutations in the gene encoding the pancreatic transcription factor hepatocyte nuclear factor 1α (HNF1A)." (PMID 26110317, 2015). "miR-224 is a novel diabetes-associated miRNA which is highly expressed in the urine of HNF1A-MODY mutation carriers and a T1DM cohort." (PMID 26110317, 2015).
diabetes (continued). "In contrast to human T2D, Maturity Onset Diabetes of the Young 3 is a monogenic disease and results from the mutations in HNF-1α transcription factor." (PMID 25716801, 2015). "Heterozygous mutations in the HNF1A gene, encoding the transcription factor hepatocyte nuclear factor-1 alpha, cause autosomal dominant inherited diabetes known as Maturity Onset Diabetes of the Young (MODY)." (PMID 24069322, 2013). "Penetrance increases with age such that approximately two thirds of HNF1A mutation carriers will have diabetes by the age of 25, and >95% by the age of 40." (PMID 23766565, 2013). "Maturity onset diabetes of the young (MODY) accounts for approximately 2% of all diabetes, with mutations in the transcription factor; hepatocyte nuclear factor 1 alpha (HNF1A) accounting for the majority of MODY cases." (PMID 24069322, 2013). "Heterozygous inheritance of an HNF4A mutation results in a similar phenotype to the patients with HNF1A mutations and accounts for approximately 5–10% of all cases of monogenic diabetes." (PMID 23766565, 2013). "Herein, we report the case of a Japanese girl who showed hepatosteatosis in early childhood before the onset of diabetes caused by HNF1A mutation." (PMID 22672869, 2012). "The coexistence of diabetes and liver adenomatosis caused by HNF1A mutation in 4 families and in 1 sporadic patient has been reported." (PMID 22672869, 2012). "The genes that code for transcription factors associated with monogenic diabetes include HNF1A, HBF1B, HNF4A, PDX1, NEUROD1, and some others." (PMID 22996131, 2012). "Of 481 participants who were free of diabetes at baseline and genotyped for the HNF1A G319S polymorphism, 388 (80.7%) G/G319, 92 (19.1%) S/G319, and 1 (0.2%) S/S319 carriers were included in the study." (PMID 21208426, 2011). "In a recent genome-wide association study, several loci including HNF1A which are involved in protein production related to insulin resistance, beta-cell function, weight gain, diabetes and/or early atherogenesis were associated with plasma CRP." (PMID 20716378, 2010). "Previous studies showed that homozygous Hnf1a mutant mice exhibit full blown diabetes, in contrast to β-cell and pancreas-specific Hnf4a mutations which only result in glucose intolerance." (PMID 20523905, 2010). "In a genome-wide association study, several loci including HNF1A which are involved in protein production related to insulin resistance, beta-cell function, weight gain, diabetes and/or early atherogenesis were associated with plasma CRP." (PMID 20716378, 2010). "The transcription factors Hnf1α and Hnf4α control pancreatic islet β-cell function and growth, and mutations in their genes cause closely related forms of diabetes." (PMID 20523905, 2010). "Pathogenic variants in the HNF1A gene may thus result in a low renal threshold for glucose, causing glycosuria with low levels of hyperglycemia even before overt diabetes develops, which can be an early marker in the natural history of the disease." (PMID 39903441, 2025). "Interestingly, the rs2637248 polymorphism in the LRMDA gene correlates with the age of diabetes onset in individuals with HNF1A mutations." (PMID 40149950, 2025). "The HNF1A locus is associated with diabetes, cholesterol levels, and CAD." (PMID 39798939, 2025). "Indeed, Rapamycin proved effective in mitigating pancreatic beta cell damage in HNF1A-associated diabetes, and it is worth considering the possibility of using such a compound also in a post-transplantation setting." (PMID 39408812, 2024). "In addition to these two conditions, HNF1A variants have been described as susceptibility factors to other types of diabetes (OMIM#222100 and #125853)." (PMID 39408812, 2024). "Consequently, approximately one in 300 people are carriers of a nucleotide sequence variant of the HNF1A gene, which protects the carriers from developing diabetes mellitus." (PMID 39902162, 2024).
diabetes (continued). "Given previously reported species differences in HNF1A-deficiency phenotypes, the potential variability introduced by chemically induced diabetes, and the ability to distinguish between circulating human and mouse insulin via ELISA, we transplanted human pseudoislets in nondiabetic mice." (PMID 37943614, 2023). "We performed functional protein analyses such as transactivation, protein expression, DNA binding, nuclear localization, and glucose stimulated insulin secretion (GSIS) assay, along with structural prediction analysis for 14 HNF1A variants found in 20 patients with monogenic diabetes." (PMID 37396188, 2023). "A subset of these features phenocopy those in humans with diabetes from HNF1A deficiency." (PMID 37943614, 2023). "Moreover, this deficit was ameliorated by treatment of transplanted grafts with glibenclamide, a sulfonylurea used in patients with diabetes with mutations in HNF1A." (PMID 37943614, 2023). "According to incomplete statistics, HNF1α can bind at least 106 target genes in the pancreas, which may explain why the mutation location of the HNF1α gene determines the age of diabetes onset." (PMID 35299962, 2022). "Why do different HNF1α mutations cause different types of diabetes?" (PMID 35299962, 2022). "For example, it could inform the timing of initiation or intensification of diabetes monitoring in HNF1A variant carriers, thereby saving time and resources and reducing the burden on affected families." (PMID 36104811, 2022). "Moreover, the penetrance of diabetes in those with HNF1A mutations is significantly influenced by polygenic type 2 diabetes risk score." (PMID 35618782, 2022). "In summary, we have identified several genetic variants that may influence the age of diabetes onset in patients with HNF1A-MODY." (PMID 36104811, 2022). "rs2637248 in the LRMDA gene is associated with age at diabetes onset in HNF1A-MODY patients." (PMID 36104811, 2022). "We next assessed whether the penetrance of pathogenic GCK variants was influenced by the background rates of diabetes similar to those of HNF1A/HNF4A-MODY." (PMID 36257325, 2022). "Having optimized the exoglycosidase plate-based assay, 1000 blood plasma samples from the HNF1A-MODY cohort were analyzed to assess α1-3,4 fucosylation levels and evaluate their diagnostic performance for the identification of cases with diabetes carrying damaging variants in the HNF1A gene." (PMID 34939081, 2022). "Finally, we explore the reason why different HNF1α mutations can lead to different types of diabetes by analyzing the protein structure and function." (PMID 35299962, 2022). "According to ACMG guidelines the HNF1A p.(Tyr163Ter) and p.(Val380CysfsTer39) are classified as pathogenic and p.(Arg271Trp) as likely pathogenic, supporting the evidence of these variants as the cause of diabetes in these families." (PMID 35592779, 2022). "HNF1A-MODY is a monogenic form of diabetes caused by variants in the HNF1A gene." (PMID 36104811, 2022). "Finally, Foxa2 has also been implicated in the regulation of Hnf4a and Hnf1a, involved in HI and monogenic diabetes." (PMID 35422763, 2022). "Thus, Haster mutations caused either functional HNF1A deficiency in pancreatic β cells, which is known to cause diabetes, or overexpression of HNF1A-dependent genes." (PMID 36202974, 2022). "Variants of the HNF1A gene are known to be associated with diabetes." (PMID 32971836, 2020). "While the mechanisms underlying changes in SGLT2 expression in DM2 (diabetes mellitus type 2) are not well understood, changes in hepatocyte nuclear factor 1α (HNF-1α) and hepatocyte nuclear factor 3β (HNF-3β) activity have been reported to contribute to alterations in SGLT2 expression." (PMID 33187206, 2020). "The mutation is in the first nucleotide of intron 2 in HNF1A, and this variant is a splicing mutation that may affect protein function and cause diabetes." (PMID 31754975, 2020).